IL6 (interleukin 6)
Diseases named in the same sentence as IL6 in open-access papers (continued):
Sharing a sentence is not in itself a finding about the gene and the disease.
cognitive decline (continued). "Chronically elevated levels of IL-6 are often associated with adverse health effects (e.g., cognitive declines, metabolic disorders)." (PMID 34823469, 2021). "In particular, cohort studies have indicated that IL-1β, IL-6 and TNFα are involved in the alteration of nutritional status, poor physical performance, loss of muscle strength, cognitive decline, and cardiological, neurological and vascular events." (PMID 34835952, 2021). "Increased serum concentrations of IL-6 and IL-8 have been associated with poor performance in memory, speed and motor function domains and predict increased risks of cognitive decline in an elderly general population." (PMID 33362607, 2020). "Six genes were associated with frailty and cognitive decline in Sargent’s recent review: IL-6 rs1800796, TNF rs1800629, IL-18 rs360722, IL1-beta rs16944, and COMT rs4680 for cognitive decline and COMT rs4646316 for frailty." (PMID 32257550, 2020). "In a follow-up study, increased circulating IL-6 level was found to be associated with accelerated cognitive decline after a 10-year follow up." (PMID 32455946, 2020). "Although astrocytes are known to be the main source of this cytokine, microglial expression of Il6 increases dramatically in the brain of aged mice, which is associated with cognitive decline." (PMID 32303185, 2020). "Proinflammatory cytokines, such as IL-1, IL-6 and TNFα, are also known to have a strong association with cognitive decline in humans and animal models." (PMID 30858535, 2019). "The most common finding has been that IL-6, measured in community-dwelling populations with a range of cognition at first assessment, is associated with subsequent cognitive decline." (PMID 31555121, 2019). "The G allele of IL-6-174C/G polymorphism shows higher IL-6 levels and associates with cognitive decline and mortality in age-related vascular disease, whereas CC allele carriers show decreased Alzheimer’s risk." (PMID 29686666, 2018). "IL6 has been extensively studied in AD, in which there are elevated levels in the blood and brain, associated with cognitive decline." (PMID 30193587, 2018). "Specifically, circulating levels of IL-6 increase with age and have been associated with rate of cognitive decline in older adults." (PMID 28344553, 2017). "In epidemiological studies higher levels of circulating inflammatory markers, especially interleukin-6 (IL-6) are associated with greater cognitive decline." (PMID 26874911, 2017). "The present findings were also consistent with previous studies that showed an association between high peripheral levels of IL-6 and cognitive decline in healthy subjects." (PMID 31162410, 2017). "Subgroup analyses for the association between high peripheral IL-6 and global cognitive decline analysis." (PMID 29358917, 2017). "In conclusion, an IDP characterized by high intake of red meat, processed meat, and peas and legumes, and low intake of whole grain, was associated with high circulating IL-6 levels and accelerated cognitive decline over a 10 year follow-up." (PMID 26874911, 2017). "The IL-6-174 G/C polymorphism (C allele caused increase of IL-6) was associated with worse cognitive function and steeper cognitive decline in participants in the Prospective Study of Pravastatin in the Elderly at Risk (PROSPER)." (PMID 26682220, 2015). "Increased plasma IL-6 level also represented a biomarker for the risk of future cognitive decline in a relatively healthy midlife (age from 30 to 54) community sample." (PMID 26682220, 2015). "Chronic inflammation, as measured by serum interleukin 6, is reported to be a risk factor for cognitive decline, cardiovascular disease, visual degradation, poor physical performance, and onset of mobility disability." (PMID 26360380, 2015). "Elevated levels of CRP and IL-6 reflect an enhanced inflammatory state and are associated with accelerated cognitive decline." (PMID 23308123, 2013).
cognitive decline (continued). "Other clinical reports point to elevated circulating levels of IL-6 as important determinant of mood symptoms and cognitive decline associated with MetS and/or obesity." (PMID 21949705, 2011). "IL6 genotyping may hold promise as a predictive tool for disease progression and cognitive decline in EBV-associated MS, offering insights for more personalized therapeutic strategies." (PMID 40663267, 2025). "IL-6 is strongly implicated in the cognitive decline observed in AD." (PMID 41009474, 2025). "Inadequate vitamin E intake has been associated with the loss of muscle strength and cognitive decline, which are features of frailty syndrome, and improvements in C-reactive protein and IL-6 levels have been observed in frail older adults with vitamin E supplementation." (PMID 41305625, 2025). "Also, immunotherapeutics such as IL-6 antagonists (IL-6RA) are effective in sustaining sensorily active microglia and decreasing the associated chronic neuroinflammatory cognitive decline, both of which are primary mechanisms of sustained neural dysfunction." (PMID 40806356, 2025). "For instance, IL-6 released by astrocytes in AD is closely associated with cognitive decline." (PMID 41009474, 2025). "Furthermore, longitudinal studies have demonstrated that elevated baseline CRP is associated with an increased risk of cognitive decline and AD development, potentially through sustained IL-6-mediated inflammatory signaling and vascular injury pathways." (PMID 41373439, 2025). "However, some inflammatory cytokines including IL-1β and IL-6 did associate with cognitive decline and lower brain volumes in our study, suggesting that the role of inflammation needs to be investigated." (PMID 39883521, 2025). "Based on our findings, physicians could develop guidelines for risk management and physical examinations in AD patients with SARS-CoV-2 infections, such as a pathogenic examination of cognitive decline and a test of serum levels of IL-6 and TNFa." (PMID 38257800, 2024). "Future research could test whether other SNPs in the IL-6 gene region regulate IL-6 expression in peripheral blood cells and potential associations with cognitive decline." (PMID 39055623, 2024). "Elevated IL-6 levels are associated with muscle weakness, impaired mobility, and cognitive decline." (PMID 39518709, 2024). "The production and signaling of IL-6 at higher levels may be associated with cognitive decline and the formation of Aβ aggregates in AD." (PMID 38606018, 2024). "Interestingly, mRNA expression levels in the prefrontal cortex indicated a significant reduction of CD3 as well as IL-6 and IL-1β in mice exposed to menthol compared to control mice, two cytokines that have been associated with cognitive decline in humans." (PMID 37187754, 2023). "The role of IL-6 in cognitive functioning has been studied also in neurodegenerative disorders, where higher serum IL-6 concentrations have been related to an increased risk of dementia and cognitive decline over time." (PMID 36915478, 2023). "Neuroinflammation is closely linked to peripheral immune activation, and cognitive decline is associated with increased peripheral inflammation, and pro-inflammatory cytokines, such as interleukin-1β (IL-1β), interleukin-6 (IL-6) and tumor necrosis factor-α (TNF-α)." (PMID 37921870, 2023). "Whether a resulting enhanced IL-6 sensitivity upon BACE inhibition contributes to the adverse events of BACE inhibitors remains unknown, but increased, pro-inflammatory IL-6 signaling is linked to cognitive decline in AD." (PMID 36810097, 2023). "Proinflammatory markers such as IL-1β and IL-6 could trigger neuroinflammation and may be associated with cognitive decline." (PMID 36494654, 2022). "Similarly, higher levels of proinflammatory cytokines, such as IL-6, were associated with greater cognitive decline and lower HS." (PMID 35250796, 2022).
cognitive decline (continued). "Elevated concentrations of inflammatory markers in the systemic circulation, such as C-reactive protein (CRP) and IL-6, are associated with the risk of dementia, although local inflammation in the CNS and systemic inflammation are suggested to contribute to cognitive decline." (PMID 35661882, 2022). "Our study supports the notion that inflammation is implicated in AD and suggests that elevated IL-6 production and signaling could be linked to cognitive decline and to peripheral metabolic dysfunction in AD." (PMID 33911072, 2021). "LMM found baseline cognitive performance, age, and IL6 score each associated with rates of cognitive change through quadratic relationships, while core AD score had a more straightforward linear relationship with cognitive decline." (PMID 34183654, 2021). "Additional evidence of microglial activation is the cerebral production of TNFalpha or IL-6 mRNA, since these cytokines are mainly released by microglia cells and a hippocampal increase in these cytokines is associated with postoperative cognitive decline." (PMID 33354426, 2020). "One neuroimaging study found that IL-6 is consistently associated with cognitive decline." (PMID 32455946, 2020). "Diverse studies highlight elevated proinflammatory cytokines, chemokines, acute phase reactants, and other inflammatory molecules in the circulation of AD patients, with some of these cytokines as interleukin-6 (IL-6), positively associated with cognitive decline and AD progression." (PMID 33224105, 2020). "Given that both TNFR1 and IL-6 are commonly regarded as pro-inflammatory cytokines, their discordant association with cognitive decline was unexpected and suggests, perhaps, that these two cytokines relate differentially to progression of disease during the preclinical phase of AD." (PMID 31555121, 2019). "Interestingly elevated systemic fibrinogen, TNFα and IL-6 in mid-life have also been linked with brain shrinkage, cognitive decline, and AD in later life." (PMID 30524237, 2018). "Additionally, increased levels of peripheral IL-1β and TNF-α, two glia-derived proinflammatory cytokines acting conjointly with IL-6, have been found to be associated with marked cognitive decline in patients with AD." (PMID 26434635, 2015). "In another large-scale, prospective occupational cohort study over 10 years, increased levels of inflammatory markers, both CRP and IL-6 at midlife, were moderately associated with a lower cognitive status but were only slightly associated with cognitive decline." (PMID 26682220, 2015). "Also, results of clinical studies point towards a relationship between IL-6 and brain function, as cognitive decline has been associated with elevated levels of IL-6 in plasma and/or serum and cerebrospinal fluid (CSF)." (PMID 26434635, 2015). "Therefore, as TL shortening is associated with decreased cognitive function in elderly, cognitive decline may be also associated with IL-6 in the elderly." (PMID 36805537, 2023). "Critically, current evidence suggests that adipose tissue is a major contributor to circulating inflammatory markers such as C-reactive protein (CRP) and interleukin-6 (IL-6), and may underline the association between adiposity and cognitive decline and dementia." (PMID 35436329, 2022). "Also, an association between cognitive decline and levels of IL-6 in CSF have been reported." (PMID 26434635, 2015). "Indeed, co-morbid conditions aggravating the outcome after ischemia entail a peripheral inflammatory response including plasma IL-6 upregulation, and high plasma IL-6 levels have been associated with worsened cognitive decline in older people and in APOE*4 carriers." (PMID 23957944, 2013). "For example, models such as the GFAP-IL6 mouse, which overexpress interleukin-6 (IL-6) in astrocytes, exhibit progressive neurodegeneration and cognitive decline, making them valuable models for studying the effects of neuroinflammation on AD progression." (PMID 40565005, 2025).
cognitive decline (continued). "It is known that IL-1, IL-8, TNF-α, and IL-6 can be predictors of cognitive decline in late middle age." (PMID 40305179, 2025). "Emerging evidence strongly suggests that inflammatory pathways (notably upregulation of pro-inflammatory factors such as NF-κB, TNF-α, and IL-6) are key contributors to cognitive decline." (PMID 40520187, 2025). "In supporting this role, a higher circulating IL-6 level correlates with worse cognitive function and steeper cognitive decline in the elderly patients." (PMID 40011296, 2025). "In AD progression, MG are activated to release cytokines (TNF-α, IL-1β, IL-6) and ROS, which exacerbate neuronal damage, impair synaptic function, and lead to cognitive decline." (PMID 41256774, 2025). "During ischemia, IL-6 activates microglia, autophagy, and endoplasmic reticulum (ER) stress, which leads to hippocampal neuron death and cognitive decline." (PMID 40305179, 2025). "This discussion supports the notion that targeting inflammatory mediators like IL-6 and TNF-alpha can be a viable strategy for managing neurodegenerative conditions associated with cognitive decline." (PMID 39906616, 2025). "IL-6 has been shown to upregulate brain-derived neurotrophic factor (BDNF), promoting neuroplasticity and potentially reducing the risk of cognitive decline." (PMID 41301508, 2025). "First, the accumulation of inflammation throughout the body mediates both cognitive decline and muscle atrophy, including C-reactive protein and interleukin-6." (PMID 40576140, 2025). "Elevated postoperative IL-6 levels have been linked to the development of POCD, with the degree of cognitive decline correlating to postoperative plasma IL-6 concentrations." (PMID 40007697, 2025). "Recent research suggests that the intensity of the initial inflammatory response, as reflected in high admission levels of cytokines such as IL-6, plays a crucial role in driving persistent neuroinflammation and subsequent cognitive decline." (PMID 40959673, 2025). "IL-6 is both a biomarker of inflammation and a predictor of frailty, cognitive decline, and poor functional performance in older adults." (PMID 41020118, 2025). "Biochemical findings centered on inflammatory cytokines, particularly IL-6 and TNF-α, which were variably associated with cognitive decline depending on timing and assessment type." (PMID 41228315, 2025). "By promoting neuroinflammation, IL-6 is believed to contribute to the development and progression of PNDs, potentially exacerbating cognitive decline and other neurological impairments." (PMID 40002918, 2025). "This activation releases pro-inflammatory cytokines, such as TNF-α, IL-6, and IL-1β, which worsen neuroinflammation, contribute to neuronal damage, and promote cognitive decline." (PMID 38963109, 2024). "IL-6 shows promise as a potential peripheral inflammatory biomarker for evaluating the severity of cognitive decline." (PMID 39080712, 2024). "Previous research had highlighted the role of IL-6 and other pro-inflammatory markers in aging and cognitive decline, supporting their potential as disease predictors." (PMID 39723155, 2024). "Over an average follow-up period of 13 years, HBP and elevated glucose, CRP, homocysteine, IL-6, and ACR concentrations were significantly associated with the risk of mortality in the individuals with incident AD/ADRD or cognitive decline." (PMID 38628973, 2024). "Through suppressing HMGB1, the levels of TNF-α, IL-1β, and IL-6 decreased, and hippocampal atrophy and cognitive decline were attenuated in the CCH model of mice." (PMID 38231472, 2024). "The upregulation of inflammatory cytokines, such as tumor necrosis factor alpha and interleukin 6, is a significant factor in cognitive decline." (PMID 39021595, 2024). "Among 13 factors included in this study, HBP, elevated glucose, CRP, homocysteine, IL-6, and elevated urine ACR were significantly associated with the risk of all-cause mortality in those with incident AD/ADRD or cognitive decline." (PMID 38628973, 2024).
cognitive decline (continued). "In Huntington’s disease (HD), marked by motor dysfunction, cognitive decline, and psychiatric symptoms, IL-6 dysregulation leads to several detrimental effects." (PMID 39015561, 2024). "For example, some studies find that high blood levels of interleukin-6 (a pro-inflammatory cytokine) are significantly linked with weaker HGS and cognitive decline, even after considering relevant confounders." (PMID 38172263, 2024). "While some studies have shown associations between inflammatory biomarkers like CRP, IL-6, and TNF-α with cognitive decline and neurodegenerative diseases, their utility as predictive factors remains uncertain." (PMID 38891863, 2024). "Primary mechanisms through which exercise exerts such an impact include the increased expression of brain-derived neurotrophic factors (BDNFs) and interleukin-6 (IL-6) in the hippocampus, subsequently enhancing memory pathways affected in cognitive decline." (PMID 38257095, 2024). "Pieces of literature on clinical and animal studies suggested that IL-6 was identified to be elevated in neurodegenerative conditions of CNS involving cognitive decline." (PMID 38091207, 2024). "In WT mice surgery induced significant cognitive decline in the Y-maze test, p = 0.019), microgliosis (p = 0.001), and increases in plasma IL-6 (p = 0.002) and HMGB1 (p = 0.001) when compared to anesthesia alone." (PMID 36927341, 2023). "Elevated levels of interleukin 6 (IL‐6), a cytokine with pro‐ and anti‐inflammatory functions, lead to cognitive decline and AD." (PMID 38680511, 2023). "An observational study of over 5000 participants found higher levels of IL-6 and CRP to be associated with worse cognitive function and steeper cognitive decline." (PMID 37178386, 2023). "More specifically, several studies showed elevated levels of IL-6 and CRP to be associated with global cognitive decline and lower performance in executive functions and memory." (PMID 37168718, 2023). "Infections cause immune dysregulation, an increase circulating pro-inflammatory mediators such as TNFα and IL-6 along with the brain levels of IL-1β and IL-6 levels, aggravating neuroinflammation and accelerating cognitive decline in older adults." (PMID 37849501, 2023). "Other proinflammatory factors, such as homocysteine and interleukin-6 (IL-6), C-reactive protein (CRP), and alpha-1-antimotrypsin, have been associated with neuroinflammation and cognitive decline." (PMID 36983685, 2023). "In a 10-year longitudinal study, higher systemic concentrations of IL-6 effectively predicted cognitive decline in late midlife." (PMID 35661882, 2022). "Longitudinal data also verified that people with higher IL-6 circulation were 1.42 times more likely to experience global cognitive decline after 2 to 7 years of follow-up than those with lower IL-6 levels." (PMID 36293430, 2022). "Higher circulating levels of IL-6 predict onset of cognitive disability in older persons as well as cognitive decline in a 10-yr." (PMID 36778590, 2022). "A meta-analysis including seven longitudinal studies presented evidence that subjects with high circulating IL-6 levels were 1.42 times more likely to experience global cognitive decline after a 2–7 year follow-up." (PMID 35479493, 2022). "Hcy and other pro-inflammatory factors such as interleukin-6 (IL-6), C-reactive protein (CRP), and alpha-1-antichymotrypsin (ACT) have been linked to neuroinflammation and cognitive decline." (PMID 34200792, 2021). "The markers related to cognitive decline were classified into the following two groups: Neuroinflammatory markers: IL-1β, IL-6, tumor necrosis factor-α (TNF-α) and genetic markers (Bdnf, Arc, Egr1) which were estimated in brain regions." (PMID 33918576, 2021). "We found significantly higher levels of all these markers between PD patients who developed cognitive decline during follow-up, except for αSyn and IL-6." (PMID 34618817, 2021).